RNU7-50P (RNA, U7 small nuclear 50 pseudogene)
Synonyms: U7.50
Gene: Small nuclear RNA gene on chromosome 11 (3,781,395 to 3,781,456, forward strand). Ensembl gene ENSG00000238304.
Homologues: Orthologues: chimpanzee U7 (92% identical), macaque U7 (81% identical). Paralogues in human: RNU7-88P (87% identical), RNU7-70P (85% identical), RNU7-34P (84% identical), RNU7-103P (82% identical), RNU7-113P (82% identical), RNU7-18P (82% identical), RNU7-194P (82% identical), RNU7-24P (82% identical), RNU7-40P (82% identical), RNU7-48P (82% identical), RNU7-104P (81% identical), RNU7-127P (81% identical), and 142 more.